SNHG5 (small nucleolar RNA host gene 5)
Diseases named in the same sentence as SNHG5 in open-access papers (continued):
Sharing a sentence is not in itself a finding about the gene and the disease.
hepatocellular carcinoma (9 papers, 2018 to 2026). A malignant tumor that arises from hepatocytes. "For example, upregulation of SNHG5 is found in hepatocellular carcinoma (HCC) and may be associated with HCC prognosis." (PMID 38438584, 2024). "To confirm the expression pattern of SNHG5 in liver CSCs, we enriched liver CSCs through inducing hepatoma spheroid formation and examined SNHG5 expression in the self-renewing spheroids and the attached cells." (PMID 35338348, 2022). "A study showed that knockdown of SNHG5 remarkably inhibited GSK3β and the Wnt/β-catenin pathway in hepatocellular carcinoma (HCC) or brain glioma cell lines." (PMID 33176855, 2020). "At the same time, SNHG5 was confirmed to play a pro-cancer role in hepatocellular carcinoma by upregulating GSK3β, activating the Wnt/β-catenin pathway and promoting EMT." (PMID 33176855, 2020). "The present study aimed to investigate the role of lncRNA small nucleolar RNA host gene 5 (SNHG5) in hepatocellular carcinoma (HCC) progression using human tissues and cell lines." (PMID 30166525, 2018). "Knockdown of SNHG5 induced apoptosis and repressed cell cycle progression, cell growth, and metastasis in hepatoma cell lines, whereas overexpression of SNHG5 had the opposite effects." (PMID 30166525, 2018). "Overall, SNHG5 exerts an oncogenic effect in hepatoma cells." (PMID 30166525, 2018). "LncRNA Small nucleolar RNA host gene 5 (SNHG5) includes six exons and two snoRNAs, competitively binding with miR-26a-5p to enhance activity of Wnt/β-catenin pathway, which advances hepatocellular carcinoma progression." (PMID 35356220, 2022). "We found that SNHG5 was up-regulated in HCC tissues and in hepatoma cell lines." (PMID 30166525, 2018).
B-cell lymphoma (6 papers, 2013 to 2022). "Small nucleolar RNA host gene 5 (SNHG5) is an lncRNA whose gene is located at the chromosomal translocation breakpoint involved in B-cell lymphoma." (PMID 32854207, 2020). "SNHG5 gene is located at the chromosomal translocation breakpoint involved in B-cell lymphoma (provided by RefSeq, July 2008)." (PMID 28033303, 2016). "LncRNA small nucleolar RNA host gene 5 (SNHG5), which is initially reported in B cell lymphoma, is oncogenic in several cancers." (PMID 35166647, 2022).
liver cancer (6 papers, 2019 to 2026). An epithelial or non-epithelial malignant neoplasm that arises from the liver. "TCGA database analysis revealed that upregulated SPATS2 was correlated with higher expression of SNHG5 in liver cancer." (PMID 35077478, 2022). "Although an increasing number of studies have elucidated the biological function of SNHG5 in liver cancer, the function and regulatory mechanism of SNHG5 in SPATS2 expression has not been reported." (PMID 35077478, 2022). "Particularly, SNHG5 exhibited an even higher HR of 4.74, accompanied by a 95% CI that ranges from 1.35 to 6.64, indicating its importance in the prognostic assessment of liver cancer." (PMID 41474641, 2026). "TCGA database showed that SNHG5 was elevated in liver cancer tissue samples." (PMID 35077478, 2022). "To verify whether SNHG5 promotes the expression of SPATS2 in human liver cancer, we performed SNHG5 gene knockdown and overexpression experiments in HepG2 cells." (PMID 35077478, 2022). "In vitro colony formation and tumor sphere formation assays showed that SNHG3, SNHG5, SNHG9, and DNACR enhance the stem‐like properties of liver cancer stem cells." (PMID 41474641, 2026). "Furthermore, in vivo experiments demonstrated that knocking down SNHG3, SNHG5, SNHG9, and DNACR inhibits the growth of liver cancer stem cells or reduces the expression of stem cell marker proteins in tumors." (PMID 41474641, 2026). "Additionally, some in vivo experiments indicated that SNHG1, SNHG5, SNHG6, SNHG8, DANCR, SNHG16, and SNHG17 can promote lung metastasis of human liver cancer cells in immunodeficient mice." (PMID 41474641, 2026).
acute myeloid leukemia (5 papers, 2021 to 2026). Acute myeloid leukemia (AML) is a group of neoplasms arising from precursor cells committed to the myeloid cell-line differentiation. "SNHG5 was associated with four items, including “acute myeloid leukemia”, “ovarian cancer”, “myeloid leukemia”, and “renal cell carcinoma”, and PSORS1C3 was associated with two items, including “DNA methylation” and “psoriasis”." (PMID 34026343, 2021). "SNHGs interact with transcription factors; for example, SP1 binds to the SNHG4 promoter to induce its upregulation, while YY1 trans-activates the SNHG5 promoter, leading to increased SNHG5 expression in acute myeloid leukemia." (PMID 41301542, 2025). "Finally, Snhg5 upregulation induced by YY1 contributes to angiogenesis in acute myelogenous leukemia." (PMID 38110334, 2023). "In acute myeloid leukemia (AML), SNHG5 interacts with PTBP1, stabilizing ATG5 mRNA and inducing autophagy in mesenchymal stromal cells (MSCs), which in turn acquire a cancer-associated fibroblast (CAF)-like phenotype, ultimately enhancing chemoresistance." (PMID 41550840, 2026).
nasopharyngeal carcinoma (5 papers, 2020 to 2024). A carcinoma arising from the nasopharyngeal epithelium. "For instance, SNHG5 has been found to promote nasopharyngeal carcinoma development via regulating miR-1179/HMGB3 axis." (PMID 34863279, 2021). "Similarly, SNHG5 in nasopharyngeal carcinoma regulates the expression of both the miR-1179/HMGB3 axis and cancer progression." (PMID 32947877, 2020).
bladder cancer (4 papers, 2018 to 2024). "SNHG5 is also associated with poor prognosis of bladder cancer, and promotes bladder cancer cell proliferation through targeting P27." (PMID 30250399, 2018). "In bladder cancer, SNHG5 overexpression promotes cancer cell proliferation by targeting p27." (PMID 35166647, 2022).
ovarian carcinoma (4 papers, 2021 to 2025). A malignant neoplasm originating from the surface ovarian epithelium. "SNHG5 was remarked downregulated in patients with ovarian cancer and associated with poor prognosis." (PMID 36105363, 2022). "Research indicates that SNHG5 sponges miR-23a, relieving its inhibition of downstream target genes, which significantly enhances ovarian cancer cell sensitivity to paclitaxel." (PMID 41301542, 2025). "Knockdown of miR-23a or overexpression of SNHG5 overcame the paclitaxel resistance in ovarian cancer cells." (PMID 36105363, 2022). "SNHG5 can act as a decoy to repress miR-23a in ovarian cancer cells." (PMID 36105363, 2022).
cervical cancer (3 papers, 2024 to 2026). A primary or metastatic malignant neoplasm involving the cervix. "In cervical cancer, SNHG5 represses miR-132 and upregulates SOX4, thereby promoting tumor proliferation and invasion, underscoring miR-132 as a shared regulatory node of SNHG5 across tumor contexts." (PMID 41550840, 2026). "Studies have shown that TUG1, SNHG5, MBNL1-AS1, HOTAIR and other lncRNAs are significantly increased in cervical cancer tissues and cell,associated with FIGO stage, lymph node metastasis, tumor size and differentiation in patients with cervical cancer." (PMID 38948025, 2024).
glioblastoma (3 papers, 2020 to 2024). The most malignant astrocytic tumor (WHO grade IV). "Recent studies of glioblastoma have shown that the LncRNA small nucleolar RNA host gene 5 (SNHG5) promotes the p38 protein and induces its activation through phosphorylation." (PMID 38254747, 2024). "The small nucleolar RNA host gene 5 (SNHG5) is another up-regulated lncRNA in glioblastoma which enhances cell proliferation and suppresses cell apoptosis in these cells." (PMID 33634032, 2020).
myeloid leukemia (3 papers, 2021 to 2022). A clonal proliferation of myeloid cells and their precursors in the bone marrow, peripheral blood, and spleen. "SNHG5 was reported as a pro-oncogenic factor stimulating proliferation of myeloid leukemia cells." (PMID 33801150, 2021).
papillary thyroid carcinoma (3 papers, 2022 to 2026). "In papillary thyroid carcinoma, SNHG5 binds and stabilizes RBM47, preventing ubiquitin-mediated degradation of FOXO3 via recruitment of USP21." (PMID 41550840, 2026).
Sepsis (3 papers, 2024 to 2026). Sepsis is defined as life-threatening organ dysfunction caused by a dysregulated host response to infection. "Small nuclear RNA host gene 5 (SNHG5) lncRNA expression is documented to be upregulated in the serum of individuals suffering from sepsis-induced AKI." (PMID 38275604, 2024). "Also, MiR-374a-3p has been reported to play a role in the pathogenesis of sepsis-induced AKI through the interaction with small nuclear RNA host gene 5 (SNHG5), such that it is able to increase apoptosis levels and cytokine release." (PMID 40217756, 2025). "Accordingly, the evidence presented in the study suggests that SNHG5 potentially modulates sepsis-induced AKI through the mediation of the miR-374a-3p/TLR4/NF-κB pathway, thereby offering novel insights into potential therapeutic strategies for this pathological condition." (PMID 38275604, 2024).
adenoma (2 papers, 2016 to 2023). A neoplasm arising from the epithelium. "We find that SNHG5 expression levels are significantly elevated both in the transition between normal tissue and adenomas and between adenomas and early stage (I) carcinoma." (PMID 28004750, 2016). "Interestingly, we find SNHG5 to be significantly up-regulated both between normal tissues and adenomas, and from adenomas to carcinoma stage I (malignant tumour), suggesting SNHG5 up-regulation as an early event in CRC development." (PMID 28004750, 2016). "RNA-seq confirmed the up-regulation of SNHG5 in CRC in a larger independent cohort of 294 normal colon mucosa samples, 33 adenomas and 280 CRC samples (n=313)." (PMID 28004750, 2016).
diffuse large B-cell lymphoma (2 papers, 2022 to 2024). "Knockdown of SNHG5 inhibited the proliferation, migration, and invasion of diffuse large B cell lymphoma cells in vitro and in vivo." (PMID 35154447, 2022).
leukemia (2 papers, 2021 to 2022). A malignant (clonal) hematologic disorder, involving hematopoietic stem cells and characterized by the presence of primitive or atypical myeloid or lymphoid cells in the bone marrow and the blood. "In chronic myeloid leukemia (CML), SNHG5 regulates the proliferation, differentiation, and apoptosis of leukemia cells by inhibiting methylation of the death receptor 4 (DR4) gene." (PMID 36033520, 2022).
lung adenocarcinoma (2 papers, 2023 to 2026). A carcinoma that arises from the lung and is characterized by the presence of malignant glandular epithelial cells. "The goal of our study was to investigate the effects of the lncRNA small nucleolar RNA host gene 5 (SNHG5) in lung adenocarcinoma (LAD) and its underlying mechanisms." (PMID 36711024, 2023). "However, in other contexts such as gastric and lung adenocarcinoma, SNHG5 expression is often reduced, and its overexpression may exhibit tumor-suppressive properties." (PMID 41550840, 2026).
lung carcinoma (2 papers, 2023 to 2024). "Furthermore, numerous studies have increasingly indicated a significant association between elevated SNHG5 expression and poor lung cancer prognosis." (PMID 38475928, 2024). "We hypothesized that the effect of SNHG5 on lung cancer cell lines was associated with EMT based on these findings and the fact that EMT has been strongly linked to tumor progression and metastasis." (PMID 36711024, 2023). "Professor Kang reported that SNHG5 is overexpressed in lung cancer, where its high expression facilitates the movement and infiltration of lung cancer cells while suppressing their apoptosis." (PMID 38475928, 2024). "In vitro, SNHG5 overexpression inhibited lung cancer cell migration and invasion, whereas SNHG5 knockdown increased LAD cell migration and invasion." (PMID 36711024, 2023). "The result showed that co-treated with Jinfukang (JFK), an effective herbal medicine formula against lung cancer, cisplatin could increase the expression of SNHG5 mRNA in another study." (PMID 36711024, 2023). "We also analyzed the role of SNHG5 in TGF-β1-induced EMT in lung cancer cells." (PMID 36711024, 2023). "In addition, our results revealed that SNHG5 plays a role in LAD advancement via modulating the epithelial-mesenchymal transition (EMT) of lung cancer tissues, indicating that SNHG5 might be a valuable target in the treatment strategy for LAD." (PMID 36711024, 2023). "SNHG5 is known to be highly downregulated in LAD patients with acquired gefitinib resistance, despite the fact that it is infrequently explored in lung cancer." (PMID 36711024, 2023).
lymph node metastasis (2 papers, 2022 to 2024). "Notably, high expression of SNHG5 was associated with lymph node metastasis in the enrolled CRC patients." (PMID 35166647, 2022).
non-small cell lung carcinoma (2 papers, 2014 to 2026). A group of at least three distinct histological types of lung cancer, including non-small cell squamous cell carcinoma, adenocarcinoma, and large cell carcinoma. "In non-small cell lung cancer, SNHG5 expression is downregulated, and its overexpression inhibits TGF-β1–induced EMT, suppressing cell migration and invasion." (PMID 41550840, 2026). "In non-small cell lung cancer, SNHG5 sponges miR-181c-5p to upregulate CBX4, thereby activating the NF-κB pathway and facilitating tumor progression." (PMID 41550840, 2026).
oral squamous cell carcinoma (2 papers, 2019 to 2023). "SNHG5 has been shown to increase cell migration and invasion in hepatocellular and oral squamous cell carcinomas, whereas we demonstrated the reverse impact of SNHG5 in LAD." (PMID 36711024, 2023).
preeclampsia (2 papers, 2022 to 2024). Preeclampsia is a hypertensive disorder of pregnancy that is characterized by new-onset hypertension with proteinuria presenting after 20 weeks of gestation, and depending on mild or severe forms may initially present with severe headache, visual disturbances, and hyperreflexia. "In vivo and in vitro studies have also reported that the overexpression of lncRNA small nucleolar RNA host gene 5 (SNHG5) in trophoblasts and mice reverses the tissue phenotype of preeclampsia in the placenta and consequently reduces tissue damage." (PMID 38534983, 2024).
prostate carcinoma (2 papers, 2022). A carcinoma that arises from epithelial cells of the prostate gland. "BCYRN1 was reported to promote prostate cancer progression, and it is described as solely an oncogene, which is also the case of LINC00152, SNHG5 and LINC00313." (PMID 35205253, 2022).
abdominal aortic aneurysm (1 paper, 2021). Enlargement and ballooning of the vessel that supplies arterial blood to the abdomen, pelvis and legs. "Therefore, SNHG5 is an important factor in pathogenesis of abdominal aortic aneurysm and thus is potential therapeutic target for abdominal aortic aneurysm." (PMID 34185955, 2021). "The findings of this study show that downregulation of SNHG5 increases expression levels of mir‐205‐5p and inhibits SMAD4 expression, thus affecting the function of vascular smooth muscle in abdominal aortic aneurysm." (PMID 34185955, 2021). "Therefore, SNHG5 is an important factor in pathogenesis of AAA and thus is potential therapeutic target for abdominal aortic aneurysm." (PMID 34185955, 2021).
acute kidney injury (1 paper, 2025). Sudden and sustained deterioration of the kidney function characterized by decreased glomerular filtration rate, increased serum creatinine or oliguria. "AKI (acute kidney injury); RUNX1 (runt-related transcription factor 1); SNHG5 (small nuclear RNA host gene 5); TLR4/NF-ĸb (toll-like receptor 4/nuclear factor-ĸB); I/R (ischemia/reperfusion); DR6 (death receptor 6)." (PMID 40217756, 2025).
acute leukemia (1 paper, 2024). A clonal (malignant) hematopoietic disorder with an acute onset, affecting the bone marrow and the peripheral blood. "In some tumors, e.g., acute leukemia, YY1 acting as a transcription factor promotes the overexpression of small nucleolar RNA host gene 5 (SNHG5), which complements and binds miR-26b and reduces angiogenesis." (PMID 38339244, 2024).
atherosclerosis (1 paper, 2025). A disease characterized by the build-up of fatty material and calcium deposition in the arterial wall resulting in partial or complete occlusion of the arterial lumen. "A further study found that serum XIST and SNHG5 levels were lower and the miR‐155 level was higher in patients with atherosclerosis than in controls." (PMID 40032652, 2025). "Multivariate analyses further identified low XIST/SNHG5 expression, a high miR‐155 level, severe stenosis, and elevated triglycerides, low‐density lipoprotein cholesterol, and high‐sensitivity C‐reactive protein to be independent predictors of a poor prognosis in patients with atherosclerosis." (PMID 40032652, 2025). "Specifically, survival was shorter in patients with atherosclerosis who had lower XIST and SNHG5 levels." (PMID 40032652, 2025).
chronic hepatitis B (1 paper, 2024). "Additionally, higher SNHG5 was found in chronic hepatitis B patients and associated with the fibrosis stage." (PMID 38438584, 2024).
clear cell renal cell carcinoma (1 paper, 2022). "For example, SNHG5 mediates miR-205-5p, which targets zinc finger E-box-binding homeobox 1 to promote the progression of clear cell renal cell carcinoma." (PMID 35346361, 2022).
colorectal tumor (1 paper, 2017). "Conversely, 81 lncRNAs appeared preferentially cytoplasmic (bottom left); these include the known cytoplasmic lncRNA SNHG5, a modulator of staufen-mediated decay that influences colorectal tumor growth (bottom right)." (PMID 29239719, 2017).
cyst (1 paper, 2026). A sac-like closed membranous structure that may be empty or contain fluid or amorphous material. "Loss of Snhg5 did not attenuate cyst formation; if anything, disease severity was mildly but not significantly exacerbated." (PMID 41507385, 2026).
diabetic macular edema (1 paper, 2022). "Notably, the Small Nucleolar RNA Host Gene 5 (SNHG5) has been correlated to the development of diabetic macular edema (DME)." (PMID 36290744, 2022).
endothelial dysfunction (1 paper, 2026). In vascular diseases, endothelial dysfunction is a systemic pathological state of the endothelium (the inner lining of blood vessels) and can be broadly defined as an imbalance between vasodilating and vasoconstricting substances produced by (or acting on) the endothelium. "SNHG5 promotes METAP2 expression by sponging miR-377-3p, leading to increased IL-8 secretion and endothelial dysfunction." (PMID 41769044, 2026).
epileptic encephalopathies (1 paper, 2025). "It was found that SNHG5 was involved in neurological disorders, SLC35F1 was involved in neurological disorders, developmental and epileptic encephalopathies resembling Rett syndrome." (PMID 40384935, 2025).
hepatitis B virus infection (1 paper, 2018). A viral infection caused by the hepatitis B virus. "The quantitative real-time PCR results showed that SNHG5 was up-regulated in both HCC tissues and hepatoma cell lines and was closely associated with tumor size, hepatitis B virus infection, histologic grade, TNM stage, and portal vein tumor thrombus (PVTT) in HCC patients." (PMID 30166525, 2018).
Hodgkins lymphoma (1 paper, 2021). A heterogeneous group of malignant lymphoid neoplasms of B-cell origin characterized histologically by the presence of Hodgkin and Reed-Sternberg (HRS) cells in the vast majority of cases. "M1 macrophages from HS2 patient showed increased levels of NINL and SNHG5, which have been associated with Hodgkin’s lymphoma lymphocytic-histiocytic predominance." (PMID 33284430, 2021).